RNU6-1215P (RNA, U6 small nuclear 1215, pseudogene)
Gene: Small nuclear RNA gene on chromosome 2 (18,583,367 to 18,583,468, reverse strand). Ensembl gene ENSG00000207170.
Homologues: Orthologues: chimpanzee U6 (99% identical), macaque U6 (92% identical), dog U6 (76% identical), mouse Gm22085 (75% identical), rabbit U6 (74% identical), pig U6 (73% identical), rat LOC120098669 (67% identical), guinea pig U6 (63% identical). Paralogues in human: RNU6-1145P (82% identical), RNU6-1200P (82% identical), RNU6-38P (82% identical), RNU6-589P (82% identical), RNU6-616P (82% identical), RNU6-1011P (81% identical), RNU6-1152P (81% identical), RNU6-15P (81% identical), RNU6-166P (81% identical), RNU6-29P (81% identical), RNU6-393P (81% identical), RNU6-41P (81% identical), and 1284 more.